IGF1 (insulin like growth factor 1)
Diseases named in the same sentence as IGF1 in open-access papers (continued):
Sharing a sentence is not in itself a finding about the gene and the disease.
sarcopenia (continued). "Notably, reduced BDNF serum concentrations were consistently observed in adulthood psychiatric pathologies, and both IGF-1 and BDNF levels have been associated with the development of sarcopenia." (PMID 29344422, 2017). "In addition, goshajinkigan was found to suppress sarcopenia via the insulin/IGF-1 signaling pathway." (PMID 28712265, 2017). "Although the precise causes of primary sarcopenia are not yet identifiable, significant alterations of endocrine–metabolic parameters, such as low insulin-like growth factor-1 (IGF-1) or free testosterone levels, often occur in sarcopenic patients." (PMID 29189738, 2017). "Thus, our data suggests that ES stimulates the expression of different isoforms of IGF-1 in muscle, guaranteeing muscle homeostasis and protection against age-related sarcopenia." (PMID 25104935, 2014). "There is evidence that insufficiency of sarcopenia-related hormones, such as GH and IGF-1, may contribute to cachexia." (PMID 22563468, 2012). "Moreover, localized expression of IGF-1 prevented sarcopenia and restored the regenerative capacity of aged skeletal muscle." (PMID 22184279, 2011). "Moreover, it is clear that over-expression of IGF-1 in muscle can protect against age-related sarcopenia." (PMID 20480032, 2010). "In addition, the relationship between IGF-1 and sarcopenia/frailty is not a one-way causal chain but a complex interaction network." (PMID 40917423, 2025). "Thus, a lower IGF-1 level can lead to a higher FOXO3 activity via the PI3K/AKT pathway, causing protein degradation and skeletal muscle atrophy, thereby resulting in the onset of sarcopenia in older adults." (PMID 41004429, 2025). "Also, IGF-1 levels were markedly lower in those suffering from sarcopenia." (PMID 39624154, 2025). "This regimen was chosen due to its ability to lower IGF-1 without any calory restriction, which might be more clinically relevant, especially for older patients who are at risk of sarcopenia as previously demonstrated." (PMID 39759002, 2024). "Additionally, heightened IGF-1 levels were correlated with a substantial rise in appendicular lean mass and whole body fat-free mass, ultimately enhancing muscle quality and acting as a robust protective factor against sarcopenia." (PMID 39507055, 2024). "The molecular mechanisms involved in this new onset acute sarcopenia are the atrogin-1/muscle atrophy F-Box (MaFbx)/muscle ring finger 1 (MuRF1) pathway, the insulin-like growth factor 1–protein kinase b–mammalian target of rapamycin (IGF-1-AKT-mTOR) and, principally, the myostatin pathway." (PMID 37408184, 2023). "In addition, growth hormone (GH) and insulin growth factor-1 (IGF-1) may be decreased in NAFLD/NASH, which may contribute to the progression of sarcopenia, since IGF-1 produced in the liver has a muscle-retaining effect." (PMID 36839249, 2023). "Some authors suggested that low IGF-1 could be a promising biomarker for sarcopenia." (PMID 35011721, 2022). "Thus, exogenous IGF-1 may have therapeutic properties in the treatment of degenerative muscle diseases, sarcopenia, and other forms of skeletal muscle atrophy." (PMID 36010642, 2022). "Finally, recent data suggests the low IGF-1 in sarcopenia may be pathological to the muscle due to its potent effects on neurons (enhancing neuronal survival, neurite formation and outgrowth in motoneurons)." (PMID 35665221, 2022). "This shows that IGF-1 may be used as a potential biomarker of sarcopenia." (PMID 34650980, 2021). "Serum IGF-1 was significantly lower among female sarcopenic subjects, with a demonstrable trend for a protective effect against sarcopenia in multiple regression models, such that each 1 ng/ml increase in IGF-1 was associated with a 1% decline in the odds of sarcopenia in women (p = 0.095)." (PMID 34650980, 2021).
sarcopenia (continued). "For example, IGF-1 has several anabolic properties (i.e., cell growth and differentiation, mitochondrial biogenesis, reduced inflammation, neuromuscular junction stability) on skeletal muscle that counteract the development of sarcopenia by activating AMPK and PGC1α." (PMID 33816541, 2021). "In patients with heart failure and sarcopenia, the level of growth hormone (GH) is increased, while the level of insulin-like growth factor-1(IGF-1) is significantly reduced, suggesting that there may be GH resistance, leading to an inhibition of skeletal muscle formation." (PMID 34957238, 2021). "Interestingly, reduced IGF-1 levels may actually contribute to sarcopenia, by limiting autophagic flux via mTORC2 and PKC." (PMID 32982690, 2020). "In addition, because of the lack of follow-up, we could not derive valuable information on the relationship between GH and IGF-1 and its long-term effects on sarcopenia patients." (PMID 32264885, 2020). "Metabolic and hormonal pathways, particularly in the growth hormone (GH)/insulin-like growth factor-1 (IGF-1) axis, are essential for metabolic regulation of bone and muscle mass, with the decline in GH and IGF-1 levels associated with both osteoporosis and sarcopenia." (PMID 32992541, 2020). "The concentration of other endocrine hormones, (Dehydroepiandrosterone, DHEAS; Sex-Hormone Binding Globulin, SHBG; and Insulin-like Growth Factor-1, IGF-1) are also associated with skeletal muscle and may be involved in the aetiology of sarcopenia since circulating concentrations change with age." (PMID 32443563, 2020). "Thus, the contribution of serum IGF-1 levels to sarcopenia and muscle wasting remains unclear in our cardiovascular surgery patients." (PMID 31581569, 2019). "Therefore, decreased IGF-1 level may be a potential biological mechanism linking link sarcopenia and low muscle mass with T2DM." (PMID 27958337, 2016). "By targeting IGF-1 and p85α proteins, miR-29 inhibited muscle protein synthesis and myogenesis since IGF-1 and p85α are well established signaling molecules for protein translation and a decrease in these proteins was observed during muscle atrophy including sarcopenia." (PMID 25018733, 2014). "Moreover, pharmacological enhancement of the IGF-1/Akt pathway, to increase protein synthesis and diminish muscle atrophy, might provide a novel therapeutic opportunity in OP-related sarcopenia." (PMID 22535191, 2013). "Interestingly, the PI3K/AKT/mTOR pathway plays an important role in translating IGF1 signals to protein synthesis and inhibiting muscle degradation and sarcopenia, and this pathway also regulates steroid, protein, ATP, and fatty acid synthesis critical in prostate carcinogenesis." (PMID 22257467, 2012). "Adults with sarcopenia showed elevated GDF-15 (k = 5, SMD: 0.26, 95% confidence interval (95%CI): 0.03-0.50, I2 = 64%, P = 0.03) and reduced IGF-1 (k = 11, SMD: -0.40, 95%CI: -0.54 - -0.27, I2 = 36%, P < 0.01) compared to controls without sarcopenia." (PMID 42202210, 2026). "Further research is needed to elucidate how these combined exercises influence key molecular pathways, such as the IGF-1/PI3K/AKT/FOXO3 axis, to enhance therapeutic strategies for sarcopenia." (PMID 41004429, 2025). "Concurrently, hormonal changes, such as declines in growth hormone, testosterone, and insulin-like growth factor-1 (IGF-1), impair muscle protein synthesis, further accelerating sarcopenia." (PMID 40151696, 2025). "Molecular and transductional pathways involved in sarcopenia include transforming growth factor beta (TGF-β), bone morphogenetic protein (BMP), and insulin-like growth factor 1 (IGF-1)." (PMID 40809315, 2025). "For instance, an ultrashort peptide-based hydrogel derived from the C-region of insulin-like growth factor 1 (IGF-1) formed supramolecular nanofibers and was used for the treatment of GC-induced sarcopenia, with a biological activity surpassing that of IGF-1." (PMID 39195060, 2024).
sarcopenia (continued). "Suggested potential sarcopenia biomarkers are myostatin (MSTN), insulin-like growth factor 1 (IGF-I), C-terminal agrin fragment (CAF), interleukin-6 (IL-6), tumor necrosis factor alpha (TNF-α), and vitamin D." (PMID 39769198, 2024). "In a zebrafish sarcopenia model, miR-128 expression is elevated, and aerobic exercise inhibits its expression, likely due to miR-128 targeting the 3′UTR of IGF-1." (PMID 39125931, 2024). "In particular, the aging-induced decline in IGF-1 accounts for the reduced PI3K activity, which in turn affects sarcopenia." (PMID 37566094, 2023). "IGF-1 was consistently lower in patients with LOLA, although we corrected for liver disease and sarcopenia in two separate matched cohort." (PMID 35215398, 2022). "A decrease in hormones critical for maintaining muscle, such as insulin-like growth factor-1 (IGF-1), testosterone, dehydroepiandrosterone (DHEA), and estrogen, are contributors to sarcopenia." (PMID 36225400, 2022). "Numerous non-coding RNAs are involved in sarcopenia pathogenesis through regulation of the TGF-β/BMP signaling pathway, IGF-1 signaling pathway, and MRF-related signaling pathway." (PMID 35053303, 2022). "In particular, sarcopenia is exacerbated by activation of the TGF-β signaling pathway, whereas it is alleviated by activation of the IGF-1 signaling pathway, the BMP signaling pathway, and the MRF-related signaling pathway." (PMID 35053303, 2022). "In disorders such as sarcopenia, IGF-1 signaling and the IGF-1 index are suppressed, resulting in muscle atrophy resulting from the combined effects of altered protein synthesis, autophagy, and impaired muscle regeneration." (PMID 36362238, 2022). "Endocrine disorders, such as low levels of 2,5-(OH) vitamin D and decreased levels of growth hormone (GH) and insulin-like growth factor-1 (IGF-1), have been observed in patients with sarcopenia." (PMID 35406642, 2022). "In conclusion, our results demonstrated that IGF-1, myostatin, and HOMA-IR levels correlated with sarcopenia status in elderly patients undergoing HD." (PMID 35371569, 2022). "Many bone-derived factors have been discovered, but here, we mainly focus on four bone factors that have a regulatory effect on muscles, namely, osteocalcin, IGF-1, RANKL and FGF-23, and seek to understand their possible therapeutic targets in sarcopenia." (PMID 34650980, 2021). "In another study, community-dwelling adults from Seoul (n = 96, age ≥ 60 years) were assessed for sarcopenia (AWGS criteria) and reported lower serum IGF-1 levels in sarcopenic patients compared with controls." (PMID 34943268, 2021). "In this review, we comprehensively summarized the latest research progress on the effects of the bone-derived cytokines FGF-23, IGF-1, RANKL, and osteocalcin on muscle and the prospects for treatment of sarcopenia." (PMID 34650980, 2021). "Indeed, both sarcopenia and PAD are accompanied by oxidative stress, skeletal muscle mitochondrial impairments, inflammation, inhibition of specific pathways regulating muscle synthesis or protection (i.e. IGF‐1, RISK, and SAFE), and activation of molecules associated with muscle degradation." (PMID 32648665, 2020). "IGF-1 and MGF levels had a stronger influence on skeletal muscle mass, which probably played vital roles in the occurrence of sarcopenia." (PMID 32264885, 2020). "GH and IGF-1 supplementation therapy reverted HFD-induced reduction in muscle strength and CSA (sarcopenia)." (PMID 29724029, 2018). "Growth hormone and insulin-like growth factor-1 (IGF-1) have been shown to have positive effects on both and decline with ageing contributing to sarcopenia and/or osteoporosis." (PMID 27572995, 2016). "Interestingly, IGF-1 was elevated in KTRs with normal muscle mass and handgrip strength (HGS) compared to those with dynapenia or sarcopenia (p = 0.037)." (PMID 41464844, 2025).
sarcopenia (continued). "The results showed that exercise intervention could effectively increase serum IGF-1 concentrations in older adult individuals with frailty (SMD = 0.53, 95%CI: 0.07–0.98, p = 0.02) and those with sarcopenia (SMD = 0.40, 95%CI: 0.19–0.61, p = 0.0002)." (PMID 40917423, 2025). "Additionally, alterations in myostatin, insulin-like growth factor 1 (IGF-1), follistatin, and creatine kinase point to significant muscle involvement, consistent with sarcopenia, weakness, and functional decline in post–COVID-19 patients." (PMID 41439932, 2025). "Patients with sarcopenia had significantly lower median IGF-1 levels (45.4 ng/ml) than those without sarcopenia (78.2 ng/ml), with a p-value of 0.009." (PMID 39624154, 2025). "Sarcopenia is also characterized by a wide range of fluctuations in various hormones, especially sex hormones such as testosterone and dehydroepiandrosterone (DHEA), and growth hormones such as growth hormone (GH) and insulin-like growth factor 1 (IGF-1)." (PMID 40894926, 2025). "Additionally, exercise elevates insulin-like growth factor-1 (IGF-1), an essential mediator of muscle protein synthesis that is often reduced in individuals with sarcopenia." (PMID 41515940, 2025). "In another study, researchers pointed out that non-coding RNAs are involved in the evolution of sarcopenia by regulating TGF-β/BMP, IGF-1, and MRF signaling pathways, and non-coding RNAs may represent biomarkers and therapeutic targets for this condition." (PMID 39409095, 2024). "IGF-1 concentrations seem to be higher in younger subjects, and the age-related decline in IGF-1 levels is considered a possible factor contributing to the development of sarcopenia." (PMID 38398421, 2024). "Low levels of IGF-1 have been found in elderly patients with sarcopenia compared to those without sarcopenia." (PMID 38525752, 2024). "Furthermore, a cross-sectional analysis involving 131 elderly individuals revealed a noteworthy decrease in IGFBP-3 levels among patients with sarcopenia, implying a contrasting function of IGFBP-3 compared to IGF-1 in skeletal muscle." (PMID 39507055, 2024). "Significantly, sarcopenia in heart failure patients with coronary artery disease (CAD) and unstable atherosclerotic plaques is marked by decreased IGF-1 expression in skeletal muscle, suggesting a potential role of IGF-1 as a positive modulator of muscle strength and function." (PMID 39203852, 2024). "In the IGF1/IRS1/Akt/mTOR pathway, decreased IGF-1 induced by liver disease and decreased ubiquitination of IRS-1 induced by epigenetic alterations block the pathway upstream and downstream respectively, leading to the development of sarcopenia." (PMID 37881635, 2023). "In 242 CLD cases, %IGF-1 was analyzed; patients with sarcopenia had significantly lower %IGF-1 levels than those without sarcopenia." (PMID 38024081, 2023). "But the hormonal constellation involved in sarcopenia does not limit to the GH/IGF-1 axis, because hormonal roles of testosterone and estrogen in modelling muscle mass and its contractile function are evident." (PMID 37490203, 2023). "In the context of improving sarcopenia in the elderly, EMS has been found to promote the secretion of myokines, particularly insulin-like growth factor-1 (IGF-1), and enhance downstream signaling pathways (Leal, Lopes & Batista, 2018; Sajer, Guardiero & Scicchitano, 2018)." (PMID 37868059, 2023). "Inflammation can also indirectly reduce the concentration of growth hormone (GH) and IGF-1 in the body, which can have a negative impact on skeletal muscle, inducing the occurrence of sarcopenia." (PMID 38092854, 2023). "Since miR-143-3p inhibits the IGF-1 signaling pathway by targeting IGFBP5, it induces sarcopenia." (PMID 35053303, 2022). "Furthermore, sarcopenia is correlated with lower levels of IGF-1 and lowered IGF-1 damages protein synthesis by inhibiting the phosphatidylinositol 3-kinase (PI3K)-Akt-mTOR pathway." (PMID 36632744, 2022).
sarcopenia (continued). "IGF-1 levels in nonsarcopenia group were higher than sarcopenia and severe sarcopenia group (60.57 [51.31–65.33] vs 46.23 [38.85–65.33] vs 29.01 [21.77–44.96] ng/ml, respectively; p = 0.001)." (PMID 35371569, 2022). "For sarcopenia, clinical trials reported different compounds, such as creatine, testosterone, bimagrumab, BCAA, androgen receptor modulators (SARM), losartan, citrulline, and IGF1 have been tested." (PMID 36010642, 2022). "they reported that IGF-1 was lower in the sarcopenia group compared with the nonsarcopenia group (all p < 0.001) and had a positive correlation with ASM index (p < 0.05)." (PMID 35371569, 2022). "In this study, IGF-1 levels were lower in the sarcopenia group than the nonsarcopenia group and negatively correlated with sarcopenia status." (PMID 35371569, 2022). "The present study aimed to clarify whether the serum insulin-like growth factor 1 (IGF-1) level, which has been reported to be related to sarcopenia and frailty, is related to LS." (PMID 35948948, 2022). "Herein, we comprehensively summarize the latest research progress on the effects of the osteokines FGF-23, IGF-1, RANKL and osteocalcin on muscle to explore whether these cytokines can be utilized to treat and prevent sarcopenia." (PMID 34650980, 2021). "Regarding biochemical parameters, the sarcopenia group had significantly lower levels of albumin (p = 0.035), IGF-1 (p < 0.001), and BCAA (p < 0.001) than the non-sarcopenia group." (PMID 33050430, 2020). "Therefore, a large-scale trial of nutritional and exercise interventions is needed to establish a treatment strategy for sarcopenia in patients with LC, especially those with low serum BCAA and IGF-1 levels." (PMID 33050430, 2020). "IGF-1 levels did not significantly differ between patients with and without sarcopenia in both males and females." (PMID 31581569, 2019). "Regarding the biochemical parameters, the levels of IGF-1 and BCAAs were significantly lower in the sarcopenia group than in the non-sarcopenia group (P < 0.001 for both)." (PMID 31878909, 2019). "Similarly, muscle size and strength, as well as IGF-1 levels decreased in mice with diet-induced NAFLD, and, as in our study, the morphological aspects of sarcopenia were observed in early stages, prior to the development of liver fibrosis." (PMID 29462978, 2018). "The reversibility of sarcopenia in a model of fatty liver mediated by supplementation of GH or IGF-1 has not yet been demonstrated." (PMID 29724029, 2018). "Among the candidates investigated, serum levels of IL-6, SPARC, MIF and IGF-1 were significantly different between normal and sarcopenia groups, but not the other biomarkers (data not shown)." (PMID 29872072, 2018). "Based on our data, since CARN promotes muscle commitment, differentiation, and IGF-1/AKT/p70S6 pathway activation, it might represent an attractive new drug for the prevention and treatment of sarcopenia." (PMID 25838869, 2015). "Reduced IGF-1 levels and/or impaired IGF-1 signal transduction may at least in part be responsible for enhanced muscle atrophy (sarcopenia), bone resorption (osteoporosis), and skin atrophy consistently observed in elderly individuals." (PMID 25520316, 2015). "During sarcopenia, impairment in insulin-like growth factor (IGF-1) were demonstrated in the muscles of old rats, but the activation of the IGF-1/Akt/mammalian target of rapamycin (mTOR) had shown to exhibit protective effect towards the skeletal muscle mass loss." (PMID 24349615, 2013). "Taken together, the existing data suggest that the IGF-1/Akt/mTOR pathway does not play a primary role in the process of sarcopenia, and that other regulators will need to be identified as possible modulators of sarcopenia." (PMID 22184279, 2011). "In addition, the research results further suggest the potential of exercise intervention in increasing serum IGF-1 concentration in specific populations, providing support for non-pharmacological treatment of sarcopenia and frailty." (PMID 40917423, 2025).